SEMA3C (semaphorin 3C)
Diseases named in the same sentence as SEMA3C in open-access papers (continued):
Sharing a sentence is not in itself a finding about the gene and the disease.
tumor (continued). "SEMA3C is frequently associated with invasion and metastasis, while SEMA3F was mainly reported to function as a tumour suppressor." (PMID 32241267, 2020). "We observed that levels of SEMA3 expression showed great heterogeneity in different cell lines as in patient tumours, with SEMA3C having the highest expression and SEMA3D having the lowest expression across all cancer cell lines." (PMID 32241267, 2020). "Among the tumor specimens with IDH mutation, mRNA levels of SEMA3B, SEMA3C, SEMA3D, SEMA3G, NRP2, PLXNA2, and CDH1 were significantly higher (p < 0.05), while SEMA3F, NRP1, ITGB3, ITGA5, and VEGFA genes were under-expressed (p < 0.05)." (PMID 33036421, 2020). "For instance, while SEMA3A binds specifically to NRP1 and SEMA3F binds to NRP2-containing holoreceptors to promote tumor cell normalization and inhibit metastasis in endothelial cells, SEMA3C shows similar affinities for NRP1 and NRP2." (PMID 32640719, 2020). "Sema3C protein, a member of the class 3 family of secreted semaphorins, play an important role in tumor development by regulating cell proliferation, migration, invasion, and angiogenesis processes." (PMID 31726800, 2019). "While SEMA3C inhibits tumor lymphangiogenesis and metastasis, its furin-cleaved form p65-SEMA3C has tumor-promoting properties in NRP2-expressing cancer cells, which was found at least in vitro, however, not yet in vivo." (PMID 30717262, 2019). "When in combination, Sema3C and NaVP components seem to have a synergistic effect on tumor development." (PMID 31726800, 2019). "In contrast with other class-3 semaphorins which function primarily as inhibitors of tumor progression, sema3C displays both pro- and anti-tumorigenic properties." (PMID 30696103, 2019). "This suggests that the certain cellular environment is required for Sema3C to augment inhibitory effects on tumor cell migration." (PMID 31726800, 2019). "In the current study, Sema3C overexpression by U87 MG cells produced inhibitory effect of blood vessel formation, tumor invasion, and adhesion in ovo similar to the effects elicited by NaVP." (PMID 31726800, 2019). "SEMA3C expression is increased in neoplastic and cancerous tissue compared to normal epithelial tissue and correlates with tumor grade and degree of angiogenesis." (PMID 30759745, 2019). "On the other hand, SEMA3C expression increases with tumor stage implying that it fills functions related to cancer progression therein supporting administration later in disease." (PMID 30759745, 2019). "On the one hand, SEMA3C is theorized to drive the rare cancer stem cell population that is thought to be responsible for treatment-resistance and tumor relapse." (PMID 30759745, 2019). "Overexpression of SEMA3C results in increased proliferation, suppressed apoptosis, increased invasion, and increased tumor volume which are mediated through increased extracellular signal-regulated kinase (ERK) signalling." (PMID 30759745, 2019). "It is worth noting that full-length SEMA3C has also been reported as a tumor suppressor factor by suppressing tumor lymphangiogenesis and metastasis." (PMID 31649890, 2019). "This Sema3C mutant also inhibited tumor lymphangiogenesis and the metastatic spread of tumor cells to lymph nodes." (PMID 30304095, 2018). "Because furin is expressed in many tumors, Sema3C is likely processed into its active form to promote tumor progression." (PMID 29642487, 2018). "Meanwhile, semaphorin 3C (Sema3C) promotes tumor migration and was highly expressed in metastatic tumor cells." (PMID 26032848, 2015). "We also showed that four members of the class 3 semaphorin family were down-regulated by metformin and aspirin, including two pro-tumor semaphorins, SEMA3C and SEMA3E." (PMID 26294325, 2015). "Of note, a very recent report demonstrates that full-length Semaphorin-3C functions as an inhibitor of tumor lymphangiogenesis and metastasis." (PMID 26319580, 2015).
tumor (continued). "We found positive significant relationship between Sema3C protein level and high tumor malignancy (p < 0.0001)." (PMID 26032848, 2015). "Patterns of gene expression associated with the 2,656-tumor dataset were found in both TCGA datasets, including the low PC4a gene expression signature of high VEGFA and low SEMA3B, SEMA3C, SEMA3F, and PLXNB1." (PMID 23667446, 2013). "We then observed that the decrease in 5-FU resistance induced by FOSL2 knockdown in the nude mouse subcutaneous tumor model could be rescued by SEMA3C overexpression." (PMID 40082673, 2025). "Among class 3 semaphorins, SEMA3A, SEMA3F, and SEMA3C play distinct roles in tumor biology." (PMID 41009819, 2025). "Moreover, inhibition or knockdown of SEMA3C suppresses tumor cell proliferation, and colony formation ability in vitro, and inhibits tumor growth in vivo." (PMID 38321460, 2024). "Plasma sema3C concentration correlated negatively with tumor grade (R = −0.62, p = 0.01)." (PMID 39457718, 2024). "Consequently, our discovery of Sema3C as a novel biomarker highlights its key role in mediating bidirectional communication between CSCs and the tumor stroma, driving a vicious cycle that accelerates HCC progression." (PMID 38956074, 2024). "Furthermore, we are now actively developing small molecule inhibitors targeting Sema3C and utilizing tumor organoids for drug screening, thereby enhancing drug development efficiency." (PMID 38956074, 2024). "Urinary sema3C concentration positively correlated with tumor size (R = 0.57, p = 0.03)." (PMID 39457718, 2024). "In TSCC cells, more than 90% of the SEMA3C-expressing cells were tumor cells, indicating that the treatment targeting SEMA3C may have little side effect." (PMID 38321460, 2024). "Furin-like pro-protein convertases (FPPC), strongly upregulating in tumor cells, could cleave signaling protein semaphorin-3 C (sema3C), which induced cytoskeletal collapse in LECs." (PMID 38566083, 2024). "In contrast, expression of SEMA3C is potentiating tumour progression in several cancer types." (PMID 38384455, 2024). "Notably, blockade of Sema3C effectively inhibits tumor growth and sensitizes HCC cells to sorafenib in vivo." (PMID 38956074, 2024). "Our single-cell sequencing results showed that SEMA3C was mainly expressed in tumor cells." (PMID 38321460, 2024). "Interestingly, urinary sema3C concentration positively correlated at the same time with tumor size, so it seems to become higher in subjects with bigger lesions." (PMID 39457718, 2024). "Moreover, semaphorin 3C upregulates androgen synthesis in LNCaP cell-derived xenograft tumors, likely contributing to the enhanced in vivo tumor growth rate post castration." (PMID 37800655, 2023). "High SEMA3C expression also promotes tumor cell angiogenesis and invasion." (PMID 37091977, 2023). "Additionally, the combination of SEMA3C knockdown and GnP therapy facilitated tumor regression and impaired peritoneal dissemination in vivo." (PMID 37537633, 2023). "Furthermore, tissue microarray analyses of 343 invasive ductal breast carcinomas revealed that SEMA3C was expressed in 90% of the cases and was positively correlated with tumor grade (p < 0.001)." (PMID 37443749, 2023). "Inhibition of SEMA3C decreased tumor formation in the xenograft model in vivo." (PMID 35785187, 2022). "Knockdown of SEMA3C expression significantly decreased tumor growth in vitro and in vivo." (PMID 35785187, 2022). "Knocking down or inhibiting SEMA3C shows the tumor inhibition in vitro or in vivo." (PMID 35785187, 2022). "Since SEMA3C is a secreted glycoprotein, tumor secreted SEMA3C may impact host myeloid/macrophage PD-L1 expression or polarization through modulation of the tumor-suppressive environment." (PMID 35785187, 2022).
tumor (continued). "In summary, our results indicate that SEMA3A, SEMA3C, SEMA3E, and SEMA3F are more often to promote tumorigenesis and associate with poor prognosis, while the other SEMA3s are more often to play a tumour suppressor role and generally associate with better prognosis." (PMID 32241267, 2020). "Indeed, both sema3F and sema3C have been observed to inhibit tumor lymphangiogenesis as well as tumor metastasis mediated by lymphatics." (PMID 30696103, 2019). "Accordingly, SEMA3C inhibition could improve breast cancer survival by reducing tumor burden and metastatic potential and may represent a novel targeted therapy for triple negative breast cancer." (PMID 30759745, 2019). "Depending on the type and malignancy grade of the tumor, Sema3C function remains controversial." (PMID 31726800, 2019). "Interestingly, in this context SEMA3C plays a role in maintaining the cohesiveness of the tumor and elevated SEMA3C expression results in decreased metastatic dissemination." (PMID 30759745, 2019). "Notably, some semaphorins such as sema3C and sema3E have also been found to potentiate tumor progression using various mechanisms." (PMID 30696103, 2019). "Immunohistochemistry would be a suitable approach in this regard; however, as SEMA3C is a secreted protein, it also stands to reason that tumor-shed SEMA3C would be present in blood or bodily fluids where it would be detectable in enzyme-linked immunosorbent assay (ELISA)-based biochemical assays." (PMID 30759745, 2019). "Moreover, SEMA3C ASO suppressed ENZ‐resistant MR49F xenograft tumor growth in vivo as monitored by tumor volume and serum PSA levels." (PMID 29348142, 2018). "Crosstalk between tumor cells and blood vessels mediated by Sema3C may also modulate tumor progression." (PMID 29642487, 2018). "These different effects of Sema3C may depend on the stage of development of the tumor, the specificity of the tissue, and the Sema3C proteolytic processing." (PMID 30304095, 2018). "More studies are needed to dissect the role of Sema3C in modulating the tumor microenvironment." (PMID 29642487, 2018). "Moreover, SEMA3C overexpression promotes orthotopic tumor growth and confers castrate‐resistant growth of LNCaP tumors." (PMID 29348142, 2018). "However, it was recently found that contrary to previous reports, sema3C functions as a potent anti-angiogenic agent that potently inhibits retinal oxygen induced angiogenesis as well as tumor angiogenesis." (PMID 28036336, 2016). "Esselens and co-workers had shown that MMP-processed Sema3C promotes tumour cell migration; furthermore, Lee and Yutzey (2011) showed that Sema3C expression is induced by Twist1, an epithelial to mesenchymal transition (EMT)-inducing transcription factor implicated in cancer progression." (PMID 26311294, 2015). "Moreover, a nude mouse subcutaneous tumor model indicated that SEMA3C overexpression could rescue the decrease in 5-FU resistance in HCT15-FR cells induced by KLF6 knockdown." (PMID 40082673, 2025). "Furthermore, analysis of the TCGA-LIHC database revealed that HCC patients with high Sema3C expression and the presence of FAP+ CAFs subset showed a significant association with advanced tumor stages/T stages compared to those with low Sema3C expression and FAP+ CAFs." (PMID 38956074, 2024). "Therefore, Sema3C may serve as a key biomarker to mediate the communication between the CSCs and tumor stroma, forming a vicious cycle in the development of HCC." (PMID 38956074, 2024). "SEMA3C has been observed to function as a potent inhibitor of angiogenesis and lymphangiogenesis, which is likely mediated by the activation of plexin-D1-dependent signal transduction in endothelial cells and lymphatic endothelial cells, resulting in the inhibition of tumor progression." (PMID 38505621, 2024).
tumor (continued). "Similarly, in prostate cancer, increased expression of SEMA3C in cancer cells was shown to upregulate epithelial to mesenchymal (EMT) markers, which was associated with increased migration and invasiveness and with increased tumour formation in mouse models." (PMID 37685898, 2023). "Furthermore, SEMA3C regulates the adhesion-detachment balance of tumor cells." (PMID 36942388, 2023). "However, expression of SEMA3C seems to correlate with tumor progression." (PMID 36942388, 2023). "Previous research showed that in hypoxic microenvironments, TWIST transcription factor interacts with NRPI to elevate SEMA3C expression, which promotes tumor cell angiogenesis and perineural invasion, suggesting that SEMA3C may mediate a key gene for immunosuppression under hypoxic microenvironment." (PMID 37091977, 2023). "Interestingly, SEMA3C has been previously demonstrated to be fundamental for NC development, and a recent tumor transcriptional profiling showed that NBM invasiveness is induced by the shutdown of SEMA3C, which functions as a pro-cohesion autocrine signal to constrain the tumoral mass." (PMID 33869187, 2021). "However, two recent studies suggest that SEMA3C may exhibit inhibitory activity on pathologic blood vessel formation and in lymphatic endothelial cells and vascular network in tumor progression." (PMID 29348142, 2018). "However, the role of Sema3C in tumor angiogenesis is controversial." (PMID 30304095, 2018). "Therefore, depending on the specificity of the tissue, Sema3C could have pro-tumorigenic effect and induce tumor angiogenesis or, contrarily, act as an anti-angiogenic factor." (PMID 30304095, 2018). "SEMA3C is known to have roles in embryogenesis, therefore, its upregulation might also confer stem-like phenotypes to cancer cells and contribute to tumor heterogeneity frequently observed in tumor histopathology of PCa patients." (PMID 28038451, 2017). "To better understand if the tumor-level correlation between class-1 FOXA1 alterations and SEMA3C expression is retained in in vitro systems, we first leveraged existing ChIP-Seq datasets from multiple recently-published reports." (PMID 38528115, 2024). "SEMA4G levels were enriched in classical tumours while the expression of SEMA3A, SEMA3C and SEMA3F was significantly enriched in basal-like PDAC." (PMID 38670629, 2024). "In summary, these findings demonstrate that Sema3C plays a critical role in enhancing HCC stemness, chemoresistance, and tumor initiation." (PMID 38956074, 2024). "We further identify NRP1 and ITGB1 as pivotal functional receptors of Sema3C, activating downstream AKT/Gli1/c-Myc signaling pathways to bolster HCC self-renewal and tumor initiation." (PMID 38956074, 2024). "To elucidate the roles of the interaction between tumor stroma and CSCs in HCC tumorigenesis, we identified Semaphorin 3C (Sema3C), as a highly upregulated protein in fibrosis and HCC tissues." (PMID 38956074, 2024). "Collectively, these results suggested that inhibition of Sema3C sensitized HCC cells to sorafenib and synergically reduced tumor growth." (PMID 38956074, 2024). "The interaction pairs via SPP1, RARRES2, NECTIN3, LGALS9, and LAMB1 showed increased signaling in the autophagy-high tumor cells, while SEMA3C, PTN, ICAM1, GAS6, and CSF1 showed decreased signaling compared with those in the autophagy-low tumor cells." (PMID 36830707, 2023). "Our studies support that Sema3C helps to maintain GSC self-renewal and drive tumor progression by promoting Wnt signaling." (PMID 37080989, 2023). "We also found enrichment for other tumor progression-related processes such as cell migration and Wnt signaling (examples of differentially expressed genes: SCUBE3, SEMA3C, WNT2)." (PMID 37085135, 2023). "Targeting both Sema3C and TCF1 resulted in sustained tumor control with almost all animals surviving." (PMID 37080989, 2023).
tumor (continued). "Ki67 staining was markedly reduced in tumors in which Sema3C and TCF1 were silenced, supporting a reduction in tumor cell proliferation." (PMID 37080989, 2023). "Our findings indicate that tumor cells with high m7G scores exert significant autocrine and paracrine effects on the cellular communication network through multiple tumor growth-promoting signals (FGF5 and SEMA3C) and immunosuppressive signals (MIF and TGF-β)." (PMID 37868988, 2023). "Therefore, we aimed to investigate whether SEMA3C silencing could impact tumor cell growth." (PMID 37443749, 2023). "SEMA3C, which binds to NRP1 and NRP2 with equivalent affinity, inhibits tumor lymphangiogenesis by targeting immature vessels sprouting." (PMID 32766254, 2020). "In general, our results show that SEMA3A, SEMA3C, and SEMA3F are primarily upregulated in cancer cells, while the rest of SEMA3s are mainly down-regulated in the tested tumours." (PMID 32241267, 2020). "Whereas SEMA3A, SEMA3C, and SEMA3F were mainly up-regulated in the tested tumours, the rest of the members SEMA3B, SEMA3D, SEMA3E and SEMA3G were primarily down-regulated with a few exceptions." (PMID 32241267, 2020). "All other SEMA3 family members show inconsistent up- or down-regulation in different cancer tumours, where SEMA3B, SEMA3D, SEMA3E, and SEMA3G are primarily down-regulated, and SEMA3A and SEMA3C are mainly up-regulated in the tested cancer types." (PMID 32241267, 2020). "In relation to the malignancy grade of the tumor, mRNA levels of SEMA3B, SEMA3C, SEMA3D, SEMA3G, PLXNA2, and CDH1 decreased while mRNA levels of SEMA3F, NRP1, ITGB3, ITGA5, and VEGFA increased with the increase of the tumor malignancy (p < 0.05)." (PMID 33036421, 2020). "As cleavage of SEMA3C by another protease, ADAMTS-1 (a disintegrin and metalloproteinase with thrombospondin motifs), stimulates tumor cell migration, proteolytic cleavage seems to be a general principle for the modulation of semaphorin signaling." (PMID 30717262, 2019). "However, sema3C also functions as a potent inhibitor of angiogenesis and lymphangiogenesis, which is likely mediated by the activation of plexin-D1-dependent signal transduction in endothelial cells and lymphatic endothelial cells, resulting in the inhibition of tumor progression." (PMID 30696103, 2019). "We generated a recombinant Plexin B1 sema domain‐Fc fusion protein called B1SP that effectively inhibited SEMA3C‐induced RTK signaling and tumor progression in vivo." (PMID 29348142, 2018). "Previous studies have shown that TGF-β1 secreted by activated CAFs was involved in the regulation of tumor cells, and our above KEGG enrichment analysis also showed that Sema3C might be related to the TGF-β1 signaling pathway." (PMID 38956074, 2024). "Additionally, CAFs within the stroma upregulate Sema3C expression via TGF-β1 secretion, thereby establishing a detrimental feedback loop between tumor and stromal cells, ultimately driving HCC progression." (PMID 38956074, 2024). "Silencing both Sema3C and TCF1 resulted in the greatest tumor control and longest animal survival." (PMID 37080989, 2023). "Homeobox A1 (HOXA1), an oncogene motivating tumor growth and tumor motility by regulating the expression of downstream pro-migration and pro-invasion genes, cyclin D1 (CCND1), MET, smoothened (SMO), and semaphorin 3C (SEMA3C)." (PMID 33917233, 2021). "Correlations between higher levels of SEMA3A, SEMA3C, and SEMA3F and type 1, 2, and 6 infiltrates (C1, C2 and C6), indicated a tumour promoter role of these gene members, as patients belonging to those categories had worse survival characterized with higher proliferation rate and enriched with TGFβ." (PMID 32241267, 2020).